RN7SL323P (RNA, 7SL, cytoplasmic 323, pseudogene)
Gene: Miscellaneous RNA gene on chromosome 8 (56,022,019 to 56,022,313, reverse strand). Ensembl gene ENSG00000241997.
Homologues: Orthologues: chimpanzee Metazoa_SRP (98% identical), macaque Metazoa_SRP (91% identical). Paralogues in human: RN7SL1 (81% identical), RN7SL3 (80% identical), RN7SL2 (80% identical), RN7SL126P (80% identical), RN7SL448P (79% identical), RN7SL664P (79% identical), RN7SL679P (79% identical), RN7SL186P (78% identical), RN7SL220P (78% identical), RN7SL650P (78% identical), RN7SL88P (78% identical), RN7SL18P (78% identical), and 700 more.